RNU6-949P (RNA, U6 small nuclear 949, pseudogene)
Gene: Small nuclear RNA gene on chromosome 1 (27,675,603 to 27,675,709, reverse strand). Ensembl gene ENSG00000206767.
Homologues: Orthologues: chimpanzee U6 (100% identical). Paralogues in human: RNU6-1060P (94% identical), RNU6-19P (94% identical), RNU6-1011P (93% identical), RNU6-12P (93% identical), RNU6-13P (93% identical), RNU6-26P (93% identical), RNU6-31P (93% identical), RNU6-32P (93% identical), RNU6-33P (93% identical), RNU6-47P (93% identical), RNU6-1 (93% identical), RNU6-1024P (93% identical), and 1289 more.